ZIC4 (Zic family zinc finger 4)
Description:
Binds to DNA.
Tractability: PROTAC: ubiquitination databases record sites on it.
Gene: Protein-coding gene on chromosome 3 (147,386,046 to 147,406,809, reverse strand). Ensembl gene ENSG00000174963.
Subcellular location: Nucleus
Subcellular location (Human Protein Atlas): Nucleoplasm; Cytosol
Gene Ontology:
Molecular function: sequence-specific double-stranded DNA binding; DNA binding; DNA-binding transcription factor activity, RNA polymerase II-specific; RNA polymerase II cis-regulatory region sequence-specific DNA binding; RNA polymerase II transcription regulatory region sequence-specific DNA binding
Biological process: central nervous system development; regulation of transcription by RNA polymerase II
Cellular component: nucleus
Genetic constraint (gnomAD): Loss-of-function variants: 15 observed, 27.93 expected, observed/expected ratio (o/e) 0.54, 90% interval 0.36 to 0.83. The upper end of that interval is the gene's LOEUF score, 0.83, which puts it in group 3 of 6, group 1 being the genes least tolerant of losing a copy. Missense variants: 512 observed, 480.3 expected, observed/expected ratio (o/e) 1.07, 90% interval 0.99 to 1.15. Synonymous variants: 220 observed, 207.9 expected, observed/expected ratio (o/e) 1.06, 90% interval 0.95 to 1.18.
Homologues: Orthologues: chimpanzee ZIC4 (99% identical), macaque ZIC4 (98% identical), pig ZIC4 (94% identical), rabbit ZIC4 (94% identical), dog ZIC4 (93% identical), mouse Zic4 (87% identical), rat Zic4 (87% identical), guinea pig ZIC4 (86% identical), zebrafish zic4 (68% identical), tropical clawed frog zic4 (67% identical). Paralogues in human: ZIC1 (63% identical), ZIC5 (62% identical), ZIC2 (60% identical), ZIC3 (58% identical), GLI2 (37% identical), GLI3 (36% identical), GLI1 (34% identical), GLIS3 (33% identical), GLIS2 (32% identical), GLIS1 (29% identical), ZXDA (25% identical), ZXDB (25% identical), and 2 more.
Diseases named in the same sentence as ZIC4 in open-access papers:
ZIC4 is named in the same sentence as 71 diseases in open-access papers, as found by Europe PMC text mining. Sharing a sentence is not in itself a finding about the gene and the disease. The quoted sentences say what the papers report.
Dandy-Walker malformation (7 papers, 2015 to 2026). "Heterozygous deletions encompassing ZIC1 and ZIC4 cause Dandy-Walker malformation, whilst in the final exon heterozygous ZIC1 variants result in a distinct phenotype of craniosynostosis with variable intellectual disability via a gain-of-function mechanism." (PMID 42028696, 2026). "Heterozygous deletions of ZIC1 and its nearby paralog ZIC4 on chromosome 3q25.1 are associated with Dandy-Walker malformation of the cerebellum, and loss of the orthologous Zic1 gene in the mouse causes cerebellar hypoplasia and vertebral defects." (PMID 26340333, 2015). "In contrast, Zic1 and Zic4 have previously been found to control the development of glutamatergic cell types in the cerebellum and combined, heterozygous loss of function mutations of these genes have been associated with Dandy-Walker Syndrome." (PMID 37365500, 2023). "Zic1 and Zic4 belong to the family of Zinc finger of the cerebellum (ZIC) protein family, whose loss of function can lead to Dandy-Walker malformation and incomplete cerebellar vermis." (PMID 35402909, 2022). "Significantly, heterozygous deletion of the homologous genes ZIC1 and ZIC4 has been shown to be involved in the Dandy-Walker malformation, a neurodevelopmental disorder characterized by hypoplasia of the cerebellar vermis and cystic dilation of the fourth ventricle." (PMID 35857265, 2022).
glioma (5 papers, 2019 to 2024). A benign or malignant brain and spinal cord tumor that arises from glial cells (astrocytes, oligodendrocytes, ependymal cells). "The simultaneous overexpression of Zic4 and miR-342-3p or miR-485-5p could mediate the biological effects on glioma cells caused by the overexpression of miR-342-3p, miR-485-5p, or Zic4 alone." (PMID 31427569, 2019). "Moloney leukemia virus 10 (MOV10)-binding circDICER1 controls the angiogenesis of gliomas via miR-103a-3p/miR-382-5p-mediated ZIC4 (Zinc finger of the cerebellum 4) expression change." (PMID 38329551, 2024). "Silencing of cZNF292, circ‐DICER1, and circ_002136 downregulated glioma tube formation through angiogenesis corresponding genes consisting of EGFR, VEGFRs, SOX13, and ZIC4 in human gliomas." (PMID 37953502, 2024). "MOV10 / circ-DICER1 / miR-103a-3p (miR-382-5p) / ZIC4 pathway plays a vital role in regulating the angiogenesis of glioma." (PMID 30621721, 2019). "The expression of Zic4 in glioma tissues and glioma cells was significantly increased compared with that in normal brain tissues and HA cells." (PMID 31427569, 2019). "The knockdown of Linc-00313 combined with the overexpression of miR-342-3p or miR-485-5p significantly inhibited the expression of Zic4, the cell proliferation, migration and invasion of glioma cells, as well as promoted apoptosis." (PMID 31427569, 2019). "Our findings proved ZIC4 is a target gene of miR-103a-3p /miR-382-5p, and miR-103a-3p/miR-382-5p regulated the angiogenesis of glioma by targeting ZIC4." (PMID 30621721, 2019). "Circ‐DICER1 was reported that it could interact with miR‐103a‐3p/miR‐382‐5p to inhibit ZIC4, which accelerated Hsp90beta in glioma‐exposed endothelial cells (GECs), and Hsp90 promoted the tumorigenesis of GECs binding to PI3K/AKT signaling pathway." (PMID 37953502, 2024). "The study further demonstrated that Zic4 was highly expressed in glioma tissues and U87 and U251 cells The silencing of Zic4 expression could inhibit the cell proliferation, migration, and invasion of U87 and U251 cells, as well as promote cell apoptosis." (PMID 31427569, 2019). "Meanwhile, the expression of ZIC4 is up-regulated in glioma tissues by detecting TCGA database." (PMID 30621721, 2019). "Consequently, MOV10/circ-DICER1/miR -103a-3p (miR-382-5p)/ZIC4 pathway plays a vital role in regulating the angiogenesis of glioma." (PMID 30621721, 2019). "In this study, the endogenous expression of UPF1, Linc-00313, miR-342-3p, miR-485-5p, Zic4, and SHCBP1 in glioma tissues and cells were determined." (PMID 31427569, 2019). "The study is the first to prove that the UPF1-Linc-00313-miR-342-3p/miR-485-5p-Zic4-SHCBP1 pathway forms a positive-feedback loop and regulates the biological behaviors of U87 and U251 cells, which might provide a new therapeutic target for glioma." (PMID 31427569, 2019). "At the same time, Zic4 could positively regulate the transcriptional expression of UPF1 and Linc-00313, thus formed a positive-feedback loop that regulated the biological behaviors of glioma cells." (PMID 31427569, 2019). "However, it has not been reported whether ZIC4 has a regulatory effect on angiogenesis of glioma." (PMID 30621721, 2019).
small cell lung carcinoma (5 papers, 2010 to 2025). Small cell lung cancer (SCLC) is a highly aggressive malignant neoplasm, accounting for 10-15% of lung cancer cases, characterized byrapid growth, and early metastasis. "Greater than 90 % of cases of anti-Zic4-associated PCD have been reported in patients with small cell lung cancer." (PMID 40687917, 2025). "In recent years, several reports have indicated Zinc-finger protein 4 (Zic4) antibodies being associated with paraneoplastic cerebellar degeneration (PCD) in patients with small cell lung carcinoma." (PMID 32450842, 2020). "Of the 61 patients with Zic4 antibody, 44 were associated with small cell lung cancer, the highest number observed, while no cases with head and neck cancer were reported." (PMID 40959352, 2025). "Autoantibodies in small lung cell carcinoma patients show cross-reactivity among ZIC1, ZIC2, and ZIC4 proteins, suggesting that immunoreactivities of the autoantibodies are directed primarily against the conserved zinc finger domains of ZIC." (PMID 20199689, 2010).
brain tumor (4 papers, 2010 to 2023). "The distinctive expression profile of ZIC4 highlights its usefulness as a molecular marker for brain tumor pathology." (PMID 20199689, 2010). "Indeed, in this GBM zebrafish model, the activation of the EGFR/RAS/ERK/AKT pathway through the zic4 enhancer induces brain tumor development with a mesenchymal GBM signature." (PMID 36982845, 2023). "To generate a brain tumour model, we used the Gal4-UAS system to induce expression of different oncogenes under the UAS promoter in the driver line Et(zic4:GAL4TA4,UAS:mCherry)hmz5, henceforth referred to as zic:Gal4." (PMID 27935819, 2017). "We examined the mRNA and protein expression of human ZIC1, ZIC2, ZIC3, ZIC4 and ZIC5 genes in meningiomas in comparison to other brain tumors, using RT-PCR, analysis of published microarray data, and immunostaining." (PMID 20199689, 2010). "However, the expression of the other ZIC genes (ZIC2, ZIC3, ZIC4, and ZIC5) has not been investigated in medulloblastoma or other brain tumors." (PMID 20199689, 2010).
hepatocellular carcinoma (4 papers, 2020 to 2025). A malignant tumor that arises from hepatocytes. "The ZIC4 expression was significantly increased when hepatoma cells with hypermethylated ZIC4 promoter (HepG2, Hep3b, and Huh7) were treated with 5-aza-Dc for 3 days." (PMID 33097694, 2020). "Additionally, epigenetic silencing of ZIC4 by enhancer of zeste homolog 2 (EZH2) mediated H3K27 trimethylation (H3K27me3) was described in hepatocellular carcinoma (HCC)." (PMID 40952541, 2025). "EZH2‐mediated H3K27me3 was involved in the repression of ZIC4 in HCC cell lines for the first time, which provided a new therapeutic target for the treatment of hepatocellular carcinoma disease." (PMID 33097694, 2020). "Altogether, these data indicate that epigenetic silencing of ZIC4 by EZH2 mediated H3K27me3 is an important mechanism in HCC and provide a new therapeutic target for the treatment of hepatocellular carcinoma disease." (PMID 33097694, 2020). "Recently, epigenetic silencing of ZIC4 was demonstrated to involve both DNA methylation and histone modification which was found to be crucial in the development and progression of hepatocellular carcinoma (HCC), and its over-expression reduced proliferation and invasiveness of HCC cells." (PMID 39266576, 2024).
medulloblastoma (4 papers, 2010 to 2025). A malignant, invasive embryonal neoplasm arising from the cerebellum. "Annotating samples by ZIC1/ZIC4 allelic expression status, copy gain within SHH, copy loss within G3/G4 medulloblastoma and ZIC1 SNV status revealed that close to 20% of SHH samples harbor genetic variants promoting ZIC1/ZIC4 expression." (PMID 39753768, 2025). "We determined the mono-allelic expression pattern of ZIC1/ZIC4 in a validation cohort of 251 medulloblastomas with matching RNA-seq and WGS data, assembled by combining publicly available and newly generated datasets." (PMID 39753768, 2025). "ZIC1, −2 and −5 are over-expressed in meningiomas, while ZIC4 is over-expressed in medulloblastomas." (PMID 27191985, 2016). "ZIC1, ZIC2, and ZIC5 are novel molecular markers for meningiomas whereas ZIC4 expression is highly selective for medulloblastomas." (PMID 20199689, 2010). "The genetic and chromatin variants of ZIC1 and ZIC4 in G4 and SHH medulloblastoma suggest a model in which the activity of ZIC TFs has context-dependent roles in UBC and granule neuron lineage cells, which cumulatively constitute the majority of the neurons in a human brain." (PMID 39753768, 2025). "Because the ZIC1/ZIC4 locus can be targeted by both genetic- and chromatin-based mechanisms, we examined the overall proportion of samples within the validation cohort medulloblastomas (251 tumors with RNA-seq and WGS) affected by either chromatin or genetic variants." (PMID 39753768, 2025). "Our observation that the ZIC1/ZIC4 locus undergoes recurrent repression in G4 medulloblastoma through hemizygous deposition of H3K27me3 on its SE prompted us to look for additional mono-allelic SEs in a cohort of 51 medulloblastoma tumors with matching H3K27ac ChIP–seq and WGS data." (PMID 39753768, 2025). "On the other hand, while SHH medulloblastoma shares a direct developmental relationship with G4 medulloblastoma, ZIC1/ZIC4 events confer a GOF phenotype." (PMID 39753768, 2025). "This pattern was associated with reduced ZIC1/ZIC4 transcript levels and was not recurrently observed in either SHH or WNT medulloblastoma." (PMID 39753768, 2025). "RT-PCR analysis revealed that ZIC4 expression is highly enhanced in medulloblastoma, in a sharp contrast to the expression levels in whole brain, while ZIC1, ZIC2 and ZIC5 are expressed both in the meningioma and medulloblastoma." (PMID 20199689, 2010). "Notably, we observe cases of G4 medulloblastoma with mono-allelic ZIC1/ZIC4 expression but without H3K27me3 deposition, suggesting that additional cryptogenic genetic/epigenetic routes to allelic silencing of ZIC1/ZIC4 exist." (PMID 39753768, 2025). "Overexpression of ZIC1/ZIC4 in G3 medulloblastoma lines followed by transcriptional profiling revealed increased expression of genes involved in neuronal differentiation, consistent with a model in which LOF of ZIC1/ZIC4 might hinder differentiation." (PMID 39753768, 2025). "Due to the lack of accurate, robust G4 medulloblastoma cell lines, we examined the functional importance of ZIC1/ZIC4 by overexpressing blue fluorescence protein (BFP) empty vector, ZIC1, ZIC4 or ZIC1 and ZIC4 together in D425 and D283 G3 medulloblastoma cell lines." (PMID 39753768, 2025).
bladder cancer (3 papers, 2016 to 2018). "ZIC4 was also associated with progression to muscle‐invasive disease in bladder cancer." (PMID 29988590, 2018). "Previous studies have shown that ZIC1 is frequently methylated in colorectal, hepatocellular, and gastric cancers while the methylation of ZIC4 was observed in bladder cancer." (PMID 27553089, 2017). "Methylation of ZIC4 in pTa bladder cancer is predictive for progression to muscle-invasive (≥ pT2) disease." (PMID 27191985, 2016).
cerebellar degeneration (3 papers, 2020 to 2025). Degeneration of the cerebellum. "We present the first reported case of paraneoplastic cerebellar degeneration with Anti-Hu and Anti-Zic4 antibodies in a 73-year-old patient with stage IV adenocarcinoma of Müllerian origin." (PMID 40687917, 2025). "Because cerebellar degeneration and corresponding symptoms are also a central hallmark of MSA, we decided to follow up on a potential role of ZIC4 in MSA patient brains by performing immunohistochemical stainings." (PMID 35997131, 2022). "The involvement of ZIC4 mutations in the Dandy–Walker cerebellar malformation and the paraneoplastic ZIC4 autoantibody–associated cerebellar degeneration could suggest a pathomechanism in MSA, by which altered ZIC4 expression could increase neuronal vulnerability." (PMID 35997131, 2022).
head and neck cancer (3 papers, 2017 to 2025). A primary or metastatic malignant neoplasm affecting the head and neck. "We presented the first reported case of PNS attributed to parotid cancer expressing the Zic4 antibody alongside a review of 21 previous cases of PNS associated with head and neck cancer." (PMID 40959352, 2025). "Our case represents the first reported instance of Zic4 antibody-positive PNS associated with head and neck cancer." (PMID 40959352, 2025). "Herein, we present the first reported case of PNS linked to Zic4 antibody-expressing parotid cancer and review 21 previous cases of PNS associated with head and neck cancers." (PMID 40959352, 2025). "Further investigations should determine the diagnostic significance of methylation of ZIC4, HHIP, and DACT2 in head and neck carcinomas." (PMID 27553089, 2017). "Further investigations should determine the detailed diagnostic significance of methylation of ZIC4, HHIP, and DACT2 in head and neck carcinomas." (PMID 27553089, 2017). "Similarly, the epigenetic status of ZIC genes, particularly their promoter methylation patterns, provides insight into diagnosis, as seen with the hypermethylation of ZIC1 and ZIC4 in ovarian and head and neck cancers." (PMID 40952541, 2025). "The analysis of the occurrence of gene promoter methylation in head and neck carcinoma cell lines indicated that CXXC4, DACT2, HHIP, ZIC1, and ZIC4 are methylated in these tumors." (PMID 27553089, 2017). "Few studies investigated the epigenetic regulation of Shh signaling in head and neck carcinomas; thus, we aimed to assess whether known negative regulators of this pathway (HHIP, PTCH1, SUFU, ZIC1, ZIC4) undergo methylation in HNSCC." (PMID 27553089, 2017).
ovarian carcinoma (3 papers, 2012 to 2020). A malignant neoplasm originating from the surface ovarian epithelium. "MethylCap-Seq has been applied to analyze methylomic patterns of ovarian tumors and results suggest that hedgehog signaling pathway members (ZIC1 and ZIC4) are DNA methylation prognostic biomarkers for ovarian cancer." (PMID 24782983, 2014). "A set of eight biomarkers: NKIRAS1/RPL15, THRB, RBPS3 (CTDSPL), IQSEC1, NBEAL2, ZIC4, LOC285205 and FOXP1, was identified as the most prominent set capable to detect both early and late stages of ovarian cancer." (PMID 23202957, 2012).
paraneoplastic cerebellar degeneration (3 papers, 2020 to 2023). A rare, immune-mediated disorder characterized by cerebellar degeneration due to the presence of an often undetected malignancy (usually carcinoma or lymphoma) in an anatomic site other than the cerebellum. "In addition, a combination of diffuse large B cell lymphoma and smoldering MM with anti-ZIC4 antibody was reported in a patient with indolent paraneoplastic cerebellar degeneration." (PMID 34942879, 2021).
glioblastoma (2 papers, 2020 to 2021). The most malignant astrocytic tumor (WHO grade IV). "MiR-342–3p can also inhibit the malignant biological behaviors of glioblastoma cells via Zic4." (PMID 32894165, 2020). "The mRNA expression of ZIC1 were highly expressed in glioblastoma patients, and ZIC3 and ZIC4 were downregulated expression." (PMID 34475426, 2021).
Intellectual disability (2 papers, 2013 to 2026). "We also detected a 3q deletion including ZIC1 and ZIC4 in a patient who underwent SNP-array analysis for intellectual disability and dysmorphisms." (PMID 23679990, 2013).
meningioma (2 papers, 2010 to 2016). A generally slow growing tumor attached to the dura mater. "Although we detected low amounts of ZIC4 transcript in one of the three-meningioma cases, the immunoreactive ZIC4 protein level in this sample was below the limit of detection (data not shown)." (PMID 20199689, 2010). "The ZIC3 and ZIC4 mRNA levels were higher in meningioma than in whole brain in one out of the three cases." (PMID 20199689, 2010). "By contrast, anti-ZIC4 staining did not produce clear nuclear staining in the meningioma cases." (PMID 20199689, 2010).
multiple system atrophy (2 papers, 2022 to 2024). Multiple system atrophy (MSA) is a neurodegenerative disorder characterized by autonomic failure (cardiovascular and/or urinary), parkinsonism, cerebellar impairment and corticospinal signs with a median survival of 6-9 years. "Notably, mutations in proximity to the ZIC4 locus are implicated in multiple system atrophy, a rare neurodegenerative disease." (PMID 39348415, 2024). "Since mutations of ZIC1 and ZIC4 and paraneoplastic autoantibodies directed against ZIC4 are associated with severe cerebellar dysfunction, we conducted immunohistochemical analyses in brain tissue of the frontal cortex and the cerebellum from 24 Multiple System Atrophy patients." (PMID 35997131, 2022).
oral cancer (2 papers, 2017 to 2018). "As one member of the zinc finger of the cerebellum family, Zic family member 4 (ZIC4) was hypermethylated and was involved in lymph node in oral cancer." (PMID 29988590, 2018). "Moreover, ZIC4 methylation correlated with lymph node involvement in oral cancer patients." (PMID 27553089, 2017).